S100A14 (S100 calcium binding protein A14)
Diseases named in the same sentence as S100A14 in open-access papers (continued):
Sharing a sentence is not in itself a finding about the gene and the disease.
tumor (continued). "In some tumor types, S100A14 seems to function as a tumor suppressor protein while in others it seems to promote tumorigenesis." (PMID 31105881, 2019). "In parallel with these in vitro data, smaller subcutaneous tumor xenografts and significantly reduced number of lung metastases were found in severe combined immunodeficient mice with knock-down of S100A14." (PMID 31105881, 2019). "Significant downregulation of S100A14 particularly at the invasive tumor islands of OSCC led us to examine the role of S100A14 in the regulation of invasive phenotype of OSCC cells." (PMID 31105881, 2019). "In line with these in vitro results, S100A14 was found to increase the growth of subcutaneous tumor xenograft in mice." (PMID 31105881, 2019). "TOV112D cells that overexpressed S100A14 also exhibited greater tumor growth potential in xenografted mice." (PMID 24939856, 2014). "In contrast, several S100 genes had similar expression levels across multiple tumour types, including S100A14, S100A13 and S100A3." (PMID 18781180, 2008). "Our study elucidated a novel mechanism by which tumor-derived S100A14 EVs promote tumor BrM." (PMID 41961478, 2026). "This also suggests that the increased expression of S100A14 in SSL might prevent tumor immune evasion in a microenvironment rich in CD8+ T and NK cells." (PMID 40806532, 2025). "This anatomical distinction may also play a role in modulating the expression and function of S100A4 and S100A14, thereby affecting tumor behavior and progression differently depending on the site of origin." (PMID 39205741, 2024). "However, in the tumor array, positive correlations were observed between S100A14 and S100A2 (R = 0.50), S100A4 (R = 0.55), S100A6 (R = 0.45), S100A7 (R = 0.47), S100A11 (R = 0.65), S100A16 (R = 0.57) and S100P (R = 0.66)." (PMID 37627239, 2023). "However, correlations were observed between S100A2 and S100A7 (R = 0.48), S100A11 (R = 0.54), S100A14 (R = 0.50), S10016 (R = 0.61) and S100P (R = 0.85), when comparing transcript levels from the tumor array." (PMID 37627239, 2023). "However, there has been limited coverage of ALB, LYZ and S100A14 in the field of PC, especially in the tumor immune microenvironment." (PMID 35953822, 2022). "Notably, the results revealed that the expression of S100A14 increased significantly with the progression of AJCC_stage, tumor grade, age and T stage." (PMID 35953822, 2022). "Notably, the effects of S100A14 are dual to some extent, depending on different biological processes and tumor types." (PMID 35953822, 2022). "Based on the progressive downregulation of S100A14 mRNA and protein from normal oral mucosa to OSCC, we previously hypothesized that S100A14 might be related to tumor suppressive functions in OSCC." (PMID 31105881, 2019). "Malignancies where S100A14 functions as a tumor promotor, strategies aimed to downregulate the S100A14 expression might be employed." (PMID 31105881, 2019). "Subsequent studies showed that S100A14 might indeed function as a tumor suppressor by inhibiting OSCC cell proliferation and/or invasion." (PMID 31105881, 2019). "On the other hand, overexpression strategies might be useful in malignancies where S100A14 functions as a tumor suppressor." (PMID 31105881, 2019). "Membranous S100A14 staining was prominent in the well-differentiated areas in the tumor." (PMID 31105881, 2019). "Correlation study results showed that S100A14 expression was positively correlated with Lauren classification (P<0.001) and differentiation (P=0.044), but negatively correlated with tumor depth (P=0.014), lymph node status (P=0.011) and distant metastasis (P=0.010)." (PMID 28726786, 2017). "The effect of S100A14 on tumor metastasis remains controversial." (PMID 28726786, 2017). "Notably, S100A14+ status and advanced tumor stage were independent prognostic factors for both disease-free and overall survival on multivariate analysis." (PMID 24939856, 2014).
tumor (continued). "S100A14 has also been shown to play vital roles in bladder tumorigenesis and tumor progression." (PMID 24939856, 2014). "Notably, Cldn2, Fetub, Fst, Orm1, S100a14 and RasGRF1 were primarily detected in the cytoplasm of bronchial normal cells and tumor cells." (PMID 19812696, 2009). "They found that S100A14 expression is associated with advanced stage (p< 0.001) and poor tumor grade (p< 0.001), but this conclusion was neither universal in all public datasets nor could it be replicated with our cohort data." (PMID 27270322, 2016). "Moreover, spatial transcriptomic/proteomic analyses could provide high-resolution insights into the spatial relationships between S100A14-expressing tumor cells and the immune landscape, not only in terms of immune cell composition but also their phenotypes within the tumor microenvironment." (PMID 40806532, 2025). "S100A14 was primarily expressed in clusters of tumor cells derived from goblet cells, and an increase in S100A14 expression was found in MSI-H tumor cells compared to MSS tumor cells." (PMID 40806532, 2025). "The co‐expression of any 1 gene from Group A (C19orf33, S100A14, and RHOD; count ≥1) and any 1 gene from Group B (CST6, CD44, TM4SF1, and TACSTD2; count ≥1) in a single tumor cell was defined as a MIC." (PMID 38864342, 2024). "Therefore, S100A14 is expected to be a predictor of the efficacy of immunotherapy in PC patients, which is consistent with the previous conclusion that S100A14 might contribute to the progression of PC by promoting immune-suppressive tumor microenvironment." (PMID 35953822, 2022). "Then RNA was extracted from tumor tissue, and qRT-PCR showed that the expression of NEAT1, IL-34, VEGFA, SPINK1, S100A14, and P4HA2 was downregulated and the expression of CCNE2 was upregulated in NEAT1 knockdown tumor tissue." (PMID 36213831, 2022). "61, 83 and 83% of tumours showed moderate to strong staining for S100A4, S100A6 and S100A14, respectively, whereas only 22% were positive for S100A2." (PMID 31123345, 2019). "Our study found that S100A14 regulates tumor cell differentiation by altering PGII and E-cadherin expression, and S100A14 expression is significantly correlated with PGII and E-cadherin expression in GC tissue." (PMID 28726786, 2017). "Of this protein family, S100A14 and S100A16 are also believed to play an important role in tumor progression." (PMID 25884418, 2015). "Moreover, we observed a positive correlation between malignant S100A14 expression and the relative percentage of CD8+ cytotoxic T cells within the tumor, particularly CD8+ CXCL13+ cells." (PMID 40806532, 2025). "The association between ESR1 and S100A8 and S100A9 expression levels was positive in Basal patients but negative in Her2, Luminal A, and Luminal B. S100P and S100A14 expression levels were higher in tumor tissues than in normal ones." (PMID 39594999, 2024). "This article aims to explore the complex interplay between S100A4 and S100A14 in CRC progression, with a particular focus on how their expression and function may vary according to the anatomical location of the tumor." (PMID 39205741, 2024). "In addition, correlations were also noted in the tumor array between S100A11 and S100A2 (R = 0.54), S100A4 (R = 0.46), S100A6 (R = 0.49), S100A13 (R = 0.67), S100A14 (R = 0.65), and S100A16 (R = 0.78)." (PMID 37627239, 2023). "However, in tumor tissues, correlations were observed between S100A7 and S100A14 (R = 0.47), and S100P (R = 0.56), suggesting crosstalk between these different S100s in tumors." (PMID 37627239, 2023). "Consistently, statistical results also demonstrated that there was a significant negative correlation between the expression of S100A14 in tumor cells and the infiltration of CD8 + T cells in the stroma." (PMID 35953822, 2022). "S100A14, a 104-amino acid protein with calcium-binding motifs, was shown to be overexpressed in 10 tumor types (including ovary, breast, and uterus), but not present in normal placenta." (PMID 27241529, 2016).
tumor (continued). "Moreover, S100A14 expression showed the highest positive correlation with the percentage of CD8+ T cells in the tumors (R = 0.30, p = 0.016), whereas a negative correlation (R = −0.29, p = 0.024) was observed in the percentage of CD4+ T cells and macrophages within tumor samples." (PMID 40806532, 2025). "And the results showed a significant negative correlation between S100A14 expression and CD8 + T cell infiltration in tumor." (PMID 35953822, 2022). "However, we observed a significant induction of S100a14 suggesting that although IL-6 and LIF may contribute to tumor features, they do not directly contribute to EMT." (PMID 36828915, 2023).
infection (2 papers, 2023 to 2025). The state of being infected such as from the introduction of a foreign agent such as serum, vaccine, antigenic substance or organism. "UPEC infection led to a statistically significant increase in IL1B transcription in the non-proliferating cell population, whereas infection significantly increased transcription of S100A14, a member of the S100 protein family, in all cell clusters." (PMID 40766562, 2025).
lymph node (1 paper, 2020). "Additionally, the S100A14 expression increase corresponded with the lymph node metastasis." (PMID 32483412, 2020).
S100A14 also shares sentences with these, for which no sentence is quoted: esophageal cancer (3 papers); metastatic tumors (2); small intestinal cancers (2); colorectal tumors (1); ductal breast carcinoma (1); endometrial carcinoma (1); epithelial ovarian tumors (1); fibrosarcoma (1); gastric tumor (1); gastrointestinal tumors (1); glaucoma (1); invasive breast carcinoma (1); liver cancer (1); melanoma (1); rectal tumors (1); scleroderma (1); serous ovarian cancer (1); squamous cell carcinoma (1); urothelial carcinoma (1); viral infections (1).